RNU1-128P (RNA, U1 small nuclear 128, pseudogene)
Gene: Small nuclear RNA gene on chromosome Y (17,789,003 to 17,789,162, reverse strand). Ensembl gene ENSG00000252513.
Homologues: Orthologues: chimpanzee U1 (98% identical), macaque U1 (83% identical). Paralogues in human: RNU1-95P (100% identical), RNU1-40P (89% identical), RNU1-97P (89% identical), RNU1-41P (88% identical), RNU1-48P (88% identical), RNU1-1 (83% identical), RNU1-2 (83% identical), RNU1-27P (83% identical), RNU1-28P (83% identical), RNU1-3 (83% identical), RNU1-4 (83% identical), RNVU1-18 (83% identical), and 132 more.